RNU4-66P (RNA, U4 small nuclear 66, pseudogene)
Gene: Small nuclear RNA gene on chromosome 6 (71,652,474 to 71,652,611, reverse strand). Ensembl gene ENSG00000202069.
Homologues: Orthologues: chimpanzee U4 (99% identical). Paralogues in human: RNU4-46P (78% identical), RNU4-52P (76% identical), RNU4-51P (75% identical), RNU4-43P (72% identical), RNU4-49P (68% identical), RNU4-15P (67% identical), RNU4-50P (66% identical), RNU4-17P (65% identical), RNU4-36P (65% identical), RNU4-10P (64% identical), RNU4-28P (64% identical), RNU4-81P (64% identical), and 82 more.